SHMT2 (serine hydroxymethyltransferase 2)
Diseases named in the same sentence as SHMT2 in open-access papers (continued):
Sharing a sentence is not in itself a finding about the gene and the disease.
tumor (continued). "Likewise, silencing SHMT2 effectively impeded the tumor growth in vivo." (PMID 33863325, 2021). "In this regard, beyond the critical identified role of SHMT2 in regulating redox homeostasis (via NADPH production), MTHFD2 was also reported to be essential since its loss resulted in an improved capacity of sensitizing tumor cells to oxidant-induced cell death." (PMID 32365833, 2020). "We hypothesized the apparent continued proliferation of SHMT2 knock down tumor cells was due to the availability of extracellular glycine in the mouse, and that a further systemic reduction of glycine might reveal an SHMT2 dependence and thereby impair tumor growth." (PMID 32903271, 2020). "However, the molecular mechanism, through which SHMT2 affects tumor proliferation and prognosis, remains unclear." (PMID 30228815, 2018). "However, it is also possible that growth retardation of Shmt2 m/m MEF is due to impaired nucleotide production, because Shmt2 also contributes to nucleotide production via one-carbon metabolism, and plays an important role in growth or survival of tumor cells and immune cells." (PMID 29323231, 2018). "In other studies, hypersuccinylation of SHMT2 through SIRT5 inhibition had been described to decrease SHMT2 activity and tumour growth." (PMID 40172090, 2025). "Higher SHMT2 expression was observed in grade III tumours compared to grades I–II, suggesting its role in tumour progression." (PMID 41154605, 2025). "Of note, comparing to LUAD tissues with earlier clinical stage, SHMT2 possessed more transcripts in those with advanced TNM stage, indicating its positive correlation with tumor stages in LUAD patients." (PMID 40432803, 2025). "The results of single-cell data suggested that SHMT2, ATIC and MTHFS were mainly expressed in tumor cells." (PMID 38625586, 2024). "As SHMT2‐Ser90 phosphorylation regulates the metabolism of LUAD cells, we next investigated the function of this phosphorylation in tumor formation." (PMID 38460155, 2024). "Finally, we verified whether SHMT2 knockdown or inhibition reduced tumor growth in vivo." (PMID 38331894, 2024). "This metabolism enrichment highlighted enzymes at the interface between glycolysis (GAPDH, ENO1, LDHA) and one-carbon metabolism (TYMS, SHMT2, MTHFR, MTHFD1), further confirming the importance of these two pathways in CIMP tumours." (PMID 38540202, 2024). "In conclusion, our results showed that SHMT2 was significantly upregulated in GC and that the expression of SHMT2 was related to TNM stage and tumour size." (PMID 38188143, 2024). "We found that mitochondrial SHMT2 and MTHFD2 negatively correlated with TDS, and that both genes were consistently related to tumor size and other aggressive clinico-pathological factors." (PMID 38331894, 2024). "Studies have shown that mitochondrial enzymes involved in the one-carbon pathway, namely SHMT2, MTHFD2, and MTHFD1L, affect the proliferation rate of tumor cells." (PMID 38881906, 2024). "Notably, studies have demonstrated that SHMT2 facilitates the conversion of serine to glycine, thereby producing active one-carbon units that are crucial for DNA and histone methylation, processes that can potentially initiate lymphomagenesis through the silencing of tumor suppressor genes." (PMID 39456851, 2024). "mRNA levels, evaluated through RT-qPCR, showed the mitochondrial enzymes SHMT2 and MTHFD2 differentially expressed in tumor samples of cSCC, the most aggressive NMSC." (PMID 36964165, 2023). "Yang and colleagues found in a recent study that serine hydroxymethyltransferase 2 (SHMT2) desuccinylation on Lys280 by SIRT5 leads to an increase in its enzymatic activity and tumor cell proliferation." (PMID 36980194, 2023). "The overexpression of the lncRNA Gm15290 exerts tumor-stimulating effects through the inhibition of miR-615-5p, which targets the genes insulin-like growth factor 2 (IGF2), AKT2, and SHMT2." (PMID 37147729, 2023).
tumor (continued). "The findings showed that AHNAK, POLE2, SHMT2, NR2F1, and TFRC expression in tumor tissues was substantially higher than in normal tissues (P < 0.05)." (PMID 38103068, 2023). "However, given that cellular metabolism is a complex process involving the activity of numerous genes, we cannot exclude that SHMT2 may also target tumor immunity and tumor progression by affecting the methylation status of mRNAs other than MYC in an m6A-dependent manner." (PMID 37932821, 2023). "Recent studies showed that serine hydroxymethyltransferase 2 (SHMT2), a crucial enzyme in the one-carbon metabolic pathway, plays a key role in tumor proliferation and development." (PMID 37108312, 2023). "In parallel, LF tumours expressed 2-fold higher SHMT1 and SHMT2 levels than did the paired adjacent lung tissue." (PMID 36615660, 2022). "Under metabolic stress, desuccinylation at lysine 280 of SHMT2 by SIRT5 enhances SHMT2 activity to accelerate cell metabolism and facilitate cell proliferation and tumour growth in vivo and in vitro." (PMID 34476002, 2021). "Conversely, an increased level of β-catenin was detected in tumor tissues derived from mice injected with HT-29 cells with SHMT2WT expression, suggesting that the β-catenin expression level correlates with the SHMT2 level in mouse tumor tissues." (PMID 33456583, 2021). "Several enzymes linked to accumulated metabolites in the malignant cells were found upregulated in tumor tissue datasets, particularly NME1 and SHMT2 mRNA expression." (PMID 33917317, 2021). "Expression levels of PKM2, SHMT2, and HIF-1α, together with interleukin 6, were also analyzed utilizing normal and tumor FFPE tissues." (PMID 31500219, 2019). "Overexpression of mitochondrial serine hydroxymethyltransferase (SHMT2) and glycine decarboxylase (GLDC) in GBM promotes tumor growth by inhibition of PKM2 activity and reduction of oxygen consumption." (PMID 31450721, 2019). "As recently described in GM, SHMT2 activity limits the activity of PKM2 and reduces oxygen consumption, thereby eliciting a metabolic state permissive of tumor cells survival in poorly vascularized tumor regions." (PMID 30857125, 2019). "In addition to the tumor number and T stage, multivariate analysis and the Cox proportional hazard regression model revealed that SHMT2 expression is an independent prognostic factor for patients with iCCA, consistent with previous SHMT2 clinical reports in other solid cancers." (PMID 30228815, 2018). "Induction of mitochondrial serine hydroxymethyltransferase (SHMT2) by c-Myc provides an elegant example of this conditional cooperation between c-Myc and HIFs in regulating metabolic circuitries of tumor cell mitochondria." (PMID 30197878, 2018). "The therapeutic effect of inhibiting SHMT2 is particularly evident in the DOX50 group, in which tumor size was 70% lower than that in the vehicle group after 20 days of treatment." (PMID 27391339, 2016). "Therefore we may argue that tumor cells with high SHMT2 level, such as Huh-7 cells, are sensitive to GLDC inhibition because excess glycine is not metabolized rapid enough via the glycine cleavage system, as evident from our results seen in the Huh-7 cells with GLDC knockdown." (PMID 27391339, 2016). "Consistently, high SHMT2 expression correlates with poor differentiation and increased invasion, while SHMT2 knockdown significantly inhibits HCC cell metastasis and tumor progression." (PMID 40738465, 2025). "SHMT (cytoplasmic, SHMT1; mitochondrial, SHMT2) catalyzes the transfer of a carbon unit from serine to tetrahydrofolate (THF), resulting in the formation of 5,10-methenyl-THF, which is crucial for nucleotide synthesis to promote rapid tumor proliferation." (PMID 40137165, 2025).
tumor (continued). "Abril and coworkers developed a small molecule inhibitor of SIRT5 called DK1-04e that inhibited the metastatic properties of breast cancer cells through desuccinylation of various metabolic enzymes, e.g., IDH, GLS, SHMT2, and PKM2, and significantly impaired tumor growth in experimental mice." (PMID 39781339, 2025). "The chi-square test showed that the expression of SHMT2 was correlated with tumour size (P = 0.034) and TNM stage (P = 0.042), but not with age, sex, pathological grade, vessel invasion, or lymph node metastasis." (PMID 38188143, 2024). "As previously noted, NSCLC patient tumor samples showed higher expression of the different enzymes of the de novo ser/gly synthesis pathway, i.e. PHGDH, PSAT1, PSPH and SHMT2, compared to the adjacent normal lung tissue, which hardly showed any expression of ser/gly pathway enzymes." (PMID 38160212, 2024). "LncRNAs play an essential role in glutamine metabolic reprogramming and serine/glycine metabolism in GI tract tumor cells, mainly by acting through the glutamine metabolism-related key enzymes GLS and GDH and the serine/glycine metabolism-related key enzyme SHMT2." (PMID 38184562, 2024). "SHMT2 may also limit pyruvate kinase 2 (PKM2) and reduce oxygen consumption to accommodate the microenvironment in tumour cells." (PMID 38188143, 2024). "Interestingly, the expression of these genes increases with tumor staging of NSCLC (p < 0.0001 for PSAT1, PSPH and SHMT2)." (PMID 38160212, 2024). "Taken together, we concluded that SHMT2 could regulate the cell cycle by targeting UHRF1 in CRC cells, which in turn promoted tumor progression, leading to poor prognosis in CRC patients." (PMID 35211429, 2022). "In addition, data from GSE26574 showed higher SHMT2 expression in tumour cells than that in normal cells, whereas data from GSE2748 revealed a consistent relationship between SHMT2 expression and clinical predictors." (PMID 36110969, 2022). "In fact, knockdown of SHMT2 in MYC-dependent cells or in vivo suppression of SHMT2, in addition to reduction of cellular NADPH, increases ROS production, triggers hypoxia-induced cell death, and impairs tumor growth." (PMID 34071836, 2021). "Immunohistochemistry staining analysis showed that SHMT2 was overexpressed in tumor tissues compared with adjacent noncancerous tissue samples (ANCT)." (PMID 33863325, 2021). "Furthermore, western blot analysis revealed decreased levels of both β-catenin in tumor tissues derived from mice injected with HCT116 and DLD-1 cells with SHMT2 knockdown." (PMID 33456583, 2021). "Moreover, SHMT2 is involved in some processes of tumorigenesis and is related to PD-L1, CMTM6, VISTA, B7-H4, Slug, and CD317 expression in the tumor microenvironment of OSCC." (PMID 33163414, 2020). "Ectopic over-expression of SHTM2 in xenograft tumors was associated with a significant increase in tumor volume, whereas we did not measure a significant change in tumor growth after SHMT2 knockdown (compare lanes 1 and 3)." (PMID 32903271, 2020). "Therefore, it appears to be controversial whether the activation of SHMT2 or intake of these supplements extends lifespan by restoring mitochondrial respiratory function and cell division or shortens lifespan by the activation of tumour growth and tumour progression." (PMID 31690790, 2019). "When a tumor cell faces hypoxia, HIF stabilization further induces SHMT2." (PMID 30197878, 2018). "Seven weeks after cell inoculation, no tumor was detected in all five mice inoculated with SHMT2-knockdown cells." (PMID 27391339, 2016). "Additionally, genes such as KCNK1, SHMT2, and PYCR1, which influence tumor metastasis and invasion through histone lactylation, may also serve as biomarkers to help track tumor progression." (PMID 40057816, 2025).
tumor (continued). "This analysis confirmed the association of TYMS, TK1, SHMT2, MTHFD2, and DHFR expressions with the main prognosis markers (hypermutation, MSI, iCluster, expression subtype, and tumour stage) while MTHFD1, and not MTHFD2, was more strongly associated with methylation status." (PMID 38540202, 2024). "Tumor invasion and metastasis are characteristics in addition to proliferation.We investigated SHMT2 knockdown’s impact on invasive metastasis in vitro.First, we observed a significant decrease in cell colony formation in MGC803, SGC7901, and HGC27 cells following SHMT2 knockdown." (PMID 37108312, 2023). "Based on their different expression patterns among normal-tumor-thrombus triples, RAB25 and GGT5 were supposed to play a consistent role in both tumorigenesis and invasion processes, while SHMT2 and CADM4 might play the opposite roles in tumorigenesis and thrombus invasion." (PMID 37328520, 2023). "Regarding the SHMT2 IHC data, 58 cases (65%) exhibited strong immunopositivity, 18 cases (21%) exhibited moderate immunopositivity, and 12 cases (14%) exhibited no or weak immunopositivity in tumor tissues." (PMID 33456583, 2021). "Myc amplification was shown to promote upregulation of SHMT2 expression in a hypoxia-inducible factor-1α (HIF-1α)-dependent manner, resulting in increased production of NADPH from NADP+, restrained cellular reactive oxygen species, and enhanced tumour cell survival." (PMID 34476002, 2021). "However, the expression of SHMT2 was not correlated with gender, tumor stage, lymph node stage, and distant metastasis stage." (PMID 34149818, 2021). "It is known that one of the OSCC microenvironment features is hypoxia and that normal epithelial cells cannot adjust at poor oxygen pressure, so a high expression of SHMT2 may promote tumor cell survival for a long time in the OSCC microenvironment." (PMID 33163414, 2020). "Furthermore, upon mitochondrial oxidative stress, the mitochondrial NADPH pool was reported to be maintained by activation of serine metabolism as knockdown of serine hydroxymethyl transferase (SHMT2) decreased cellular NADPH/NADP+ and impaired tumor growth in MYC‐dependent cells." (PMID 33005744, 2020). "In addition, we detected SHMT2 expression in 6 paired tumor and nontumor tissues using Western blotting." (PMID 30228815, 2018). "Moreover SHMT2-knockdown Huh-7 cells failed to form tumor xenograft after subcutaneous inoculation into nude mice." (PMID 27391339, 2016). "The results showed a significant correlation between the SHMT2 gene and tumour proliferation, DNA repair and replication, cellular cycle, and MYC genes, which suggested that SHMT2 might be involved in the appearance and development of tumours in a variety of processes." (PMID 38188143, 2024). "The immunohistochemistry results confirmed the SHMT2 knockdown efficiency in the tumor tissue, and the HIF1α staining results were consistent with the in vitro findings, indicating that the HIF1α in the shSHMT2 group was not normally expressed during tumor hypoxia." (PMID 37108312, 2023). "However, SHMT2 knockdown with or without benzoate treatment did not inhibit xenograft tumor growth." (PMID 32903271, 2020). "However, while we achieved inducible SHMT2 knockdown in vivo, this did not prevent tumor growth." (PMID 32903271, 2020). "However, tumor growth was not affected by SHMT2 knockdown with or without benzoate treatment." (PMID 32903271, 2020). "Our study showed that SHMT2decreased tumor cell survival by affecting HIF1α expression, which, in turn, altered the downstream VEGF–STAT3 pathway.Concerning how SHMT2 affected HIF1α, we identified SHMT2’s enzymatic and non-enzymatic roles as contributing to its effect." (PMID 37108312, 2023). "According to the microarray data, we identified a positive significance between increasing expression of SHMT2 and recurrent OSCC, and there was no distinct difference in target protein expression among different tumor sizes, lymph node stages, and lymph node metastasis." (PMID 33163414, 2020).
infection (8 papers, 2018 to 2025). The state of being infected such as from the introduction of a foreign agent such as serum, vaccine, antigenic substance or organism. "Infection drove increases in the levels of ATF4 targets Atf3, Shmt2, and Mthfd2, similar to our results in cultured cells." (PMID 40811546, 2025). "Knockdown of ATF4 by lentiviral shRNA infection reduced RNA levels of PSAT1 and SHMT2 in T315I-Bcr-Abl-32D cells." (PMID 38987326, 2024). "As expected, infection induced MTHFD2 and SHMT2 in an ATF4-dependent manner." (PMID 40811546, 2025).
adenocarcinoma (4 papers, 2020 to 2025). A common cancer characterized by the presence of malignant glandular cells. "Conversely, one sample with adenocarcinoma features showed less CPT1A associated with less SHMT2, MTHFD2, and PSAT1 expression." (PMID 33218188, 2020).
gastrointestinal tumors (4 papers, 2021 to 2024). "Previous studies revealed that SHMT2 expression is significantly induced in gastrointestinal tumors and caused the malignant progression and poor prognosis, including EC." (PMID 37932821, 2023).
metabolic disease (4 papers, 2021 to 2025). A congenital disorder (due to inherited enzyme abnormality) or acquired (due to failure of a metabolically important organ) disorder resulting from an abnormal metabolic process. "Moreover, the disruption of SHMT2 function has been linked to developmental anomalies that may predispose individuals to metabolic disorders." (PMID 40738465, 2025). "On the one hand, the epileptic metabolic disorders pathway whose candidate genes for validation were Dld, Slc25a1A, and Shmt2." (PMID 40076950, 2025). "Although this study focused on embryonic development, it underscores the importance of SHMT2 in cellular proliferation and differentiation, processes that are often dysregulated in metabolic diseases." (PMID 40738465, 2025). "Further research is warranted to fully elucidate SHMT2 role and to explore its potential as a therapeutic target for metabolic disorders." (PMID 40738465, 2025). "These variations are particularly suitable for identifying the linkage disequilibrium of the SHMT2 gene, which plays a role in developing complex metabolic diseases." (PMID 38347107, 2024). "However, global SHMT2 knockout is unsuitable for simulating metabolic diseases that usually impact adults." (PMID 38347107, 2024).
colorectal (1 paper, 2018). "However, whether post-translational modification affects the level of SHMT2 protein in tumorigenesis and how the upregulation of SHMT2 is involved in colorectal carcinogenesis are unknown." (PMID 30367038, 2018).
hematological disorders (1 paper, 2024). "These insights highlight SHMT2 as a significant therapeutic target for developing interventions aimed at ameliorating these hematological disorders." (PMID 39456851, 2024).
SHMT2 also shares sentences with these, for which no sentence is quoted: cholangiocarcinoma (2 papers); hereditary clear cell renal cell carcinoma (2); Huntington disease (2); idiopathic pulmonary fibrosis (2); Intellectual disability (2); neurodevelopmental disorder (2); neurological disorders (2); papillary renal cell carcinoma (2); rectal carcinoma (2); adrenal cancer (1); adrenocortical carcinoma (1); Alzheimer disease (1); amyloid diseases (1); anal carcinoma (1); Anxiety (1); Arrhythmia (1); brain cancer (1); breast tumor (1); Cachexia (1); campylobacteriosis (1); co-infection (1); collagenous colitis (1); Constipation (1); Crohn disease (1); diseases of the salivary gland (1); gastritis (1); hearing loss (1); hemorrhage (1); Hyperglycemia (1); Hypertension (1).
A further 33 diseases each share a sentence with SHMT2 in 1 paper.